TBR1 (T-box brain transcription factor 1)
Description:
Transcriptional repressor involved in multiple aspects of cortical development, including neuronal migration, laminar and areal identity, and axonal projection. As transcriptional repressor of FEZF2, it blocks the formation of the corticospinal (CS) tract from layer 6 projection neurons, thereby restricting the origin of CS axons specifically to layer 5 neurons (By similarity).
Synonyms: TBR-1; AUTS5; IDDAS; TES-56
Tractability: PROTAC: ubiquitination databases record sites on it.
Gene: Protein-coding gene on chromosome 2 (161,416,297 to 161,425,870, forward strand). Ensembl gene ENSG00000136535.
Subcellular location: Nucleus
Gene Ontology:
Molecular function: protein binding; DNA-binding transcription factor activity; DNA-binding transcription factor activity, RNA polymerase II-specific; RNA polymerase II cis-regulatory region sequence-specific DNA binding; chromatin DNA binding; DNA binding; protein kinase binding
Biological process: negative regulation of DNA-templated transcription; brain development; cell fate specification; commitment of neuronal cell to specific neuron type in forebrain; regulation of neuron projection development; regulation of transcription by RNA polymerase II; cerebral cortex development; chromatin remodeling; gene expression; positive regulation of DNA-templated transcription; regulation of DNA-templated transcription
Cellular component: nucleus; chromatin
Genetic constraint (gnomAD): Loss-of-function variants: 6 observed, 48.21 expected, observed/expected ratio (o/e) 0.12, 90% interval 0.067 to 0.25. The upper end of that interval is the gene's LOEUF score, 0.25, which puts it in group 1 of 6, group 1 being the genes least tolerant of losing a copy. Missense variants: 615 observed, 858.76 expected, observed/expected ratio (o/e) 0.72, 90% interval 0.67 to 0.77. Synonymous variants: 416 observed, 377.51 expected, observed/expected ratio (o/e) 1.1, 90% interval 1.02 to 1.2.
Gene-disease validity (ClinGen):
ClinGen rates the evidence that TBR1 causes each of these diseases.
complex neurodevelopmental disorder (autosomal dominant): Definitive. A disorder that involves more than one phenotype associated with the central nervous system, including but not limited to intellectual disability, autism, and seizures (epilepsy).
Homologues: Orthologues: chimpanzee TBR1 (100% identical), macaque TBR1 (100% identical), dog TBR1 (99% identical), pig TBR1 (99% identical), rat Tbr1 (99% identical), mouse Tbr1 (99% identical), tropical clawed frog tbr1 (86% identical), zebrafish tbr1b (80% identical), Drosophila melanogaster ocm (19% identical), Drosophila melanogaster H15 (17% identical), Caenorhabditis elegans mab-9 (17% identical), Drosophila melanogaster mid (17% identical), and 7 more. Paralogues in human: EOMES (47% identical), TBX21 (33% identical), TBX2 (21% identical), MGA (20% identical), TBX3 (20% identical), TBX5 (20% identical), TBX18 (19% identical), TBX15 (19% identical), TBX1 (19% identical), TBX4 (18% identical), TBX6 (18% identical), TBX19 (18% identical), and 4 more.
Diseases named in the same sentence as TBR1 in open-access papers:
TBR1 is named in the same sentence as 50 diseases in open-access papers, as found by Europe PMC text mining. Sharing a sentence is not in itself a finding about the gene and the disease. The quoted sentences say what the papers report.
autism (25 papers, 2009 to 2025). Persistent deficits in social interaction and communication and interaction as well as a markedly restricted repertoire of activity and interest as well as repetitive patterns of behavior. "This evolutionarily conserved connection defect makes mice an excellent model for TBR1-linked autism." (PMID 39012916, 2024). "Our previous study indicated that BLA deficiency is critical to the autism-linked behavioral deficits exhibited by Tbr1+/– mice." (PMID 39012916, 2024). "Our study emphasizes the defective synchronization at a whole-brain scale caused by Tbr1 deficiency and implies a potential beneficial effect of deep brain stimulation at the amygdala for TBR1-linked autism." (PMID 39012916, 2024). "We found that TBR1, a critical gene implicated in autism, was strongly up-regulated in neurons carrying the intronic variation, comparing to wild-type neurons." (PMID 33948885, 2021). "The antibody against autism-linked transcription factor T-Box Brain 1 (TBR1), identifies developing neuroblasts of the subplate and cortical plate, which provide the first pioneer neurons of the developing cortical networks." (PMID 33005129, 2020). "Echoing the mutations identified in patients, Tbr1+/− mice exhibit autism-like behaviors, including reduced social interaction, impaired learning and memory, and aberrant cognitive flexibility." (PMID 30792833, 2019). "Our study suggests that increased neuronal activity can improve multiple autism-like behaviors in Tbr1+/− mice, confirming that impaired neural circuits and activity are general features caused by Tbr1 deficiency." (PMID 30792833, 2019). "Tbr1+/− mice can serve as a suitable model for revealing how an autism causative gene controls neuronal circuits, neural activity, and autism-related behaviors." (PMID 30792833, 2019). "TBR1 influences the expression (upregulation or downregulation) of genes associated with autism or dyslexia." (PMID 26578866, 2015). "Tbr1+∕− mice thereby serve as a model to elucidate how mutation of an autism causative gene influences brain wiring and impairs neuronal activity and consequently results in autism-like behaviors." (PMID 26578866, 2015). "Intriguingly, both the marginal zone and subplate have been shown to highly express some of the genes most significantly linked to neurodevelopmental disorders such as autism and schizophrenia, such as Reelin and TBR1." (PMID 26379512, 2015). "Additionally, another study reported that mice with haploinsufficiency of the autism-associated gene, T-box, Brain 1 (Tbr1), displayed impairments in olfactory discrimination." (PMID 32580781, 2020). "The Tbr1 null animal was chosen because Tbr1 is a developmentally related transcription factor that binds, among other targets, the promoter of a gene called autism susceptibility candidate 2 (Auts2), named for its implication in autism susceptibility in the frontal cortex." (PMID 24245670, 2013). "In other brain regions, key autism susceptibility genes included FOXP1 (caudate and putamen), MEF2C and SATB2 (cortical plate), and TBR1 and NR4A2 (subplate)." (PMID 41279531, 2025). "Moreover, optogenetic stimulation at BLA enhanced whole-brain synchronization and increased nose-to-nose investigations by Tbr1+/– mice of conspecific unfamiliar mice, implying that deep brain stimulation of amygdala may represent a potential treatment for TBR1-linked autism." (PMID 39012916, 2024). "Here, we apply a whole-brain immunostaining and quantification platform to demonstrate impaired structural and functional connectivity and aberrant whole-brain synchronization in a Tbr1+/– autism mouse model." (PMID 39012916, 2024). "This revealed that differentiated control-iPSCs had higher levels of TBR1-positive cells than differentiated autism-iPSCs." (PMID 32826066, 2021). "Previous reports showed that the downregulated expression of TBR1 stimulated the expression of autism-related genes, potentially leading to the occurrence of autism." (PMID 34567661, 2020).
autism (continued). "As found for other autism-like behaviors, systemic administration of D-cycloserine fully ameliorated the defect of olfactory discrimination we observed in Tbr1+/− mice." (PMID 30792833, 2019). "Previous reports have shown that Tbr1+/− mice, a mouse model for autism, exhibit reduced social interaction, cognitive inflexibility, and defective associative memory." (PMID 30792833, 2019). "This scenario is supported by the observation that local infusion of D-cycloserine, an NMDAR coagonist, into amygdalae ameliorates the autism-like behaviors exhibited by Tbr1+/− mice." (PMID 30792833, 2019). "Thus, our evidence supports the hypothesis that Tbr1 deficiency alters neural circuits (by changing axonal projection and neuronal activation), resulting in autism-like behaviors, and that these defects can be improved by increasing neuronal activity via D-cycloserine treatment." (PMID 30792833, 2019). "If impairment of amygdala activation, and particularly reduced NMDAR activity, is critical for autism-like behaviors in Tbr1+∕− mice, the activation of amygdalar neurons should ameliorate the behavioral defects of Tbr1+∕− mice." (PMID 26578866, 2015). "Addressing these questions will further elucidate the roles of TBR1 in brains and potentially impact on autism research." (PMID 26578866, 2015). "Because administration of D-cycloserine to the amygdala is sufficient to ameliorate the behavioral defects of Tbr1+∕− mice, the etiology of autism-like behaviors in Tbr1+∕− mice very likely involves amygdala defects." (PMID 26578866, 2015). "Tbr1+∕− mice constitute the first genetic mouse model to show that defects in amygdalar circuits and activity result in autism-like behaviors." (PMID 26578866, 2015). "However, whether these autism-linked mutants of Tbr1 disrupt the ability of Tbr1 to sense neuronal activation signals and whether the N374H mutation influences the DNA binding ability or protein stability to further affect TBR1 function remains unclear." (PMID 25309323, 2014). "As a demonstration of MSET’s applicability, enrichment of autism gene lists was evaluated in a set of microarray results from the developing neocortex of T-box brain gene 1 (Tbr1) null mice, a putative model for autism genetics." (PMID 24245670, 2013). "Cacna2d3, Chd8, and Tbr1 are associated with autism and ID generally but not with any named syndromes." (PMID 39431203, 2024). "If whole-brain synchronization is indeed a critical aspect of autism-linked deficits, we speculate that TBS at the BLA may improve to some extent the social behaviors of Tbr1+/– mice." (PMID 39012916, 2024). "Thus, our study reveals unexpected changes in brain connectivity attributable to Tbr1 deficiency and further illuminates a potential treatment for TBR1-related autism by means of deep brain stimulation at the amygdala." (PMID 39012916, 2024). "Indeed, Tbr1+/− heterozygous mice display autism-like phenotypes, such as impaired social interactions, abnormal ultrasonic vocalization and defects in associative memory and cognitive flexibility." (PMID 35781633, 2022). "Since Grin2b encodes a critical subunit of N-methyl-D-aspartate receptor (NMDAR), an important glutamate receptor involved in learning/memory and a variety of neurological disorders including autism and schizophrenia, TBR1 regulates neuronal activity and functions by controlling Grin2b expression." (PMID 30792833, 2019). "Tbr1 haploinsufficiency results in autism-like behaviors in mice." (PMID 26578866, 2015). "Further work is necessary to understand the individual actions of other TBR1 downstream target genes and how their dysfunction could generate autism-like behaviors." (PMID 26578866, 2015). "Interestingly, our recent data demonstrate that Grin2b induction upon behavioral stimulation is impaired in Tbr1+/- mice, which thus show autism-like behaviors." (PMID 25309323, 2014).
autism (continued). "The Tbr1 null neocortex was observed to be enriched specifically for autism-associated gene sets, and not for any other mental health disorders included in our analysis." (PMID 24245670, 2013). "Thus, these behavioral analyses strongly support that Tbr1+∕− mice exhibit autism-like behaviors." (PMID 26578866, 2015).
autism spectrum disorder (18 papers, 2014 to 2024). A spectrum of developmental disorders that includes autism, and Asperger syndrome. "Tbr1 encodes a T-box transcription factor and is considered a high confidence autism spectrum disorder (ASD) gene." (PMID 35123407, 2022). "For example, TBR1 is a TF recently implicated in Intellectual Disability (ID) and Autism Spectrum Disorder (ASD)." (PMID 34665801, 2021). "Recurrent de novo variants in the TBR1 transcription factor are implicated in the etiology of sporadic autism spectrum disorders (ASD)." (PMID 30250039, 2018). "Tbr1 has been associated with autism spectrum disorders, regulates corticofugal cell identities during development, and represses target genes including Fezf2 during development of the corticospinal tract." (PMID 28112643, 2017). "Recently, recurrent de novo disruptive mutations in the TBR1 gene have been found in patients with autism spectrum disorders (ASDs)." (PMID 26578866, 2015). "In turn, its repression target TBR1 has also been identified as one of the genes with recurrent de novo mutations in autism spectrum disorders (ASD)." (PMID 26321900, 2015). "T-brain-1 (TBR1), a critical neuron-specific transcription factor for forebrain development, has been recognized as a high-confidence risk gene for autism spectrum disorders." (PMID 25309323, 2014). "For instance, Tbr1, Chd7, and Hdac2 are autism spectrum disorder risk genes." (PMID 36791184, 2023). "Tbr1 is a high-confidence autism spectrum disorder (ASD)gene encoding a transcription factor with distinct pre- and postnatal functions.Postnatally, Tbr1 conditional knockout (CKO) mutants andconstitutive heterozygotes have immature dendritic spines and reduced synapticdensity." (PMID 32294447, 2020). "TBR1 is a neuron-specific transcription factor involved in brain development and implicated in a neurodevelopmental disorder (NDD) combining features of autism spectrum disorder (ASD), intellectual disability (ID) and speech delay." (PMID 36579832, 2023). "Mutations in Tbr1, a high-confidence ASD (autism spectrum disorder)-risk gene encoding the transcriptional regulator TBR1, have been shown to induce diverse ASD-related molecular, synaptic, neuronal, and behavioral dysfunctions in mice." (PMID 31680851, 2019). "Recently, TBR1 has emerged as a master regulator of transcription in autism spectrum disorders (ASD) by regulating the expression of ASD-related genes that are critical for cortical development, including RELN, GRIN2B and AUTS22,8–10." (PMID 30250039, 2018). "TBR1 is necessary for neuronal differentiation of NPC and is a potential master regulator in autism spectrum disorders and SZ." (PMID 33005129, 2020).
Intellectual disability (13 papers, 2015 to 2025). "In ASD, frameshift pathogenic TBR1 variants leading to premature stop codons occurring later in the coding sequence have been associated with intellectual disability and language delay." (PMID 32948248, 2020). "Pathogenic variants expected to lead to truncated TBR1 proteins were all associated with intellectual disability." (PMID 32948248, 2020). "The authors highlighted that among 10 ASD individuals with a TBR1 pathogenic variant, 100% showed a language delay and 80% had intellectual disability." (PMID 32948248, 2020). "Both a microdeletion of the chromosome region that contains 2q24.2 and de novo mutations of the TBR1 gene have been found in patients with intellectual disabilities." (PMID 26578866, 2015). "While loss of TBR1 is a known contributor to cortical malformations and intellectual disability, its specific role in the pathogenesis of WDSTS remains unclear." (PMID 40956618, 2025). "Among these genes, TBR1—a putative transcription factor (TF)—is highly expressed in glutamatergic early-born cortical neurons; it dictates the expression of other risk genes, controls cortical development, and is implicated in intellectual disability." (PMID 31699123, 2019). "Microdeletions causing the disruption of TBR1 give rise to severe speech and language deficits, autistic-like problems, and moderate to severe intellectual disability, while larger deletions encompassing TBR1 cause delayed or absent speech and language and intellectual disability." (PMID 26136701, 2015). "Taken together, TBR1 is closely associated with ASDs, schizophrenia and intellectual disability." (PMID 26578866, 2015). "In addition to ASDs, TBR1 is also associated with intellectual disability." (PMID 26578866, 2015). "Mutations and microdeletions that cause TBR1 loss-of-function in humans are associated with cerebral cortex malformations that are accompanied by ASD and intellectual disability." (PMID 35781633, 2022). "In conclusion, together with previous results, our findings support the concept that Tbr1 levels must be finely regulated, both temporally and spatially, to prevent the occurrence of brain malformations that underlie ASD and intellectual disability." (PMID 35781633, 2022). "TBR1 binds to CASK, which is a membrane-associated guanylate kinase playing a key role in intellectual disability." (PMID 32948248, 2020). "Pathogenic variants in TBR1 are often associated with severe forms of ASD, including intellectual disability and language impairment." (PMID 32948248, 2020). "Based on this case report, we discuss the role of TBR1 in general brain development, language development, intellectual disability and other symptoms of ASD." (PMID 32948248, 2020). "De novo TBR1 mutations, microdeletions and variants causing loss-of-function of this TF are found recurrently in individuals with brain malformations that accompany ASD and intellectual disability." (PMID 35781633, 2022). "Notably, in most previous reports on ASD and intellectual disability, PAX6, TBR1 and FOXP2 were either deficiently expressed or had lost functions." (PMID 31699123, 2019). "Importantly, this patient presents with no intellectual disability or language impairment, despite a de novo heterozygous frameshift pathogenic variant in TBR1, leading to an early premature termination codon (c.26del, p.(Pro9Leufs*12))." (PMID 32948248, 2020). "The TBR1-CASK complex regulates the expression of genes involved in brain development and of several candidate genes for ASD and intellectual disability." (PMID 32948248, 2020).